INS (insulin)
Diseases named in the same sentence as INS in open-access papers (continued):
Sharing a sentence is not in itself a finding about the gene and the disease.
Hepatic steatosis (continued). "To date, only few data are available about association of post-transplant hepatic steatosis with serum adipokines and insulin resistance as the main mechanisms of hepatic steatosis." (PMID 32728230, 2020). "Surgical removal of PAT followed by 16-week HFD feeding was associated with aggravated hepatic steatosis (p = 0.008) and higher basal (p < 0.05) and glucose-stimulated insulin levels (p < 0.01)." (PMID 32843711, 2020). "CAP evaluation showed hepatic steatosis in 36.3% of the patients (8/22), associated with higher BMI, waist circumference, insulin, and ALT." (PMID 31275240, 2019). "Our results indicate that elevated hepatic LCN2 and IL-1β are closely associated with hepatic insulin impairment, hepatic steatosis, and excessive lipid circulation, consistent with previous reports." (PMID 31892368, 2019). "Inflammation is also important, as it leads to insulin resistance, interrupting lipid metabolism and causing liver steatosis and cellular damage, leading to fibrosis." (PMID 31330878, 2019). "Histological liver steatosis grades are inversely associated with hepatic and skeletal muscle insulin sensitivity measured by a euglycemic hyperinsulinemic clamp with 3-[3H]-glucose in non-diabetic individuals." (PMID 31447675, 2019). "A common variant in patatin-like phospholipase domain containing protein 3 (I148M) was associated with hepatic steatosis whereas insulin response was quite normal." (PMID 31521175, 2019). "An increase in ChREBP in HCV G1 infection is associated with maintaining insulin signalling sensitivity during fatty liver disease, induces expression of lipogenic enzyme acetyl-CoA carboxylase and fatty acid synthase genes." (PMID 31332246, 2019). "It has been reported that FoxO1 improves hepatic insulin signaling and fatty liver disease, although the underlying mechanisms remain to be elucidated." (PMID 31246177, 2019). "Second-generation antipsychotics (SGAs) are known to increase cardiovascular risk through several physiological mechanisms, including insulin resistance, hepatic steatosis, hyperphagia, and accelerated weight gain." (PMID 29740394, 2018). "For example, the induction of hepatic steatosis was found to be a risk factor leading to insulin sensitivity, metabolic abnormalities and visceral obesity." (PMID 30540839, 2018). "This suggests that SGLT2 inhibitors prevent hepatic steatosis not only via its insulin-independent glucose-lowering effect and caloric loss but also via modulating energy homeostasis and balance in adipose and non-adipose tissues." (PMID 29402900, 2018). "LCAD is a key enzyme in mitochondrial fatty acid β-oxidation, and LCAD deficiency causes hepatic steatosis and hepatic insulin resistance." (PMID 30574122, 2018). "Our in silico analysis showed that PTEN was one of the significantly inhibited upstream regulators, and loss of PTEN function is already known to enhance insulin sensitivity and promote hepatic steatosis, steatohepatitis, fibrosis, and liver cancer." (PMID 30429453, 2018). "Primary outcome measures comprised established risk parameters (insulin sensitivity, hepatic steatosis index (HSI), fatty liver index (FLI) and a pro-inflammatory score)." (PMID 28604592, 2017). "The high-fat diet was more detrimental for peripheral insulin sensitivity, and it caused liver steatosis." (PMID 28638152, 2017). "Dietary fish oil increases adipose tissue mass in ICR (imprinting control regions) mice, but is associated with improved insulin sensitivity and reduced hepatic steatosis." (PMID 28173868, 2017). "Given that fats in liver are known to cause both hepatic and peripheral desensitivity to insulin, sustained excessive calorie intake will strongly increase the chance of developing hepatic steatosis over time." (PMID 27632189, 2016).
Hepatic steatosis (continued). "We recently found that aliskiren attenuated hepatic steatosis by up-regulating fatty acid oxidation-related genes with increasing systemic insulin sensitivity in methionine-choline-deficient (MCD) diet-fed mice." (PMID 26732252, 2016). "The lipid droplet-associated proteins FSP27/CIDEC and LSDP5, regulated directly by PPARγ and PPARα, are associated with hepatic steatosis and insulin sensitivity." (PMID 26770990, 2016). "Our data has shown a high-calorie high-complex carbohydrate diet selectively increases ChREBPβ expression in the liver, and this is associated with increased hepatic steatosis yet improved insulin sensitivity." (PMID 27992582, 2016). "Restored autophagy in liver, in turn, can facilitate lipid droplets degradation and thus improve fatty liver-associated pathologies such as hepatic steatosis and inflammation, ultimately leading to local and systemic insulin resistance." (PMID 26930600, 2016). "Ceramide and ceramide-derived sphingolipids are structural components of membranes, and these components are associated with insulin resistance, oxidative stress, and inflammation, which suggest that they play a role in the development of liver steatosis." (PMID 27629750, 2016). "The loss of GPAT1 leads to impaired insulin sensitivity despite preventing hepatic steatosis in ob/ob mice." (PMID 25849936, 2015). "Hepatic PPARα associated with the attenuation of insulin signaling and hepatic steatosis was upregulated by 2.35 fold in HFD rats." (PMID 24638096, 2014). "The mechanisms under fatty liver are still elusive; insulin resistance, which is the most widely accepted pathogenesis, is proposed to be associated with hepatic steatosis." (PMID 24369486, 2013). "The liver also becomes insulin resistant during the development of T2D, and this is associated with increases in the levels of hepatic steatosis." (PMID 23483669, 2013). "Over-expression of human apoC-III in transgenic mice predisposes the animal to diet induced hepatic steatosis and hepatic insulin resistance." (PMID 23554788, 2013). "In obesity, the impaired ability to up-regulate LPL by insulin exacerbates hepatic postprandial lipid load, thus causes hepatic steatosis." (PMID 23554788, 2013). "Rap1-deficient mice showaccumulation of abdominal fat, hepatic steatosis, and high-fasting plasma levelsof insulin, glucose, cholesterol, and alanine aminotransferase." (PMID 23791526, 2013). "We have previously demonstrated in leptin-deficient ob/ob mice that AMP-DNM treatment reduced liver steatosis associated with a restoration of liver insulin signaling." (PMID 23056165, 2012). "Activation of JNK and IKK has been suggested to be associated with hepatic steatosis and impaired insulin signal transduction." (PMID 22355328, 2012). "Future studies will be needed to determine if this receptor mediates the effects of osteocalcin on energy metabolism and to clarify the mechanisms underlying insulin resistance and hepatic steatosis in GPRC6A−/− mice." (PMID 19050760, 2008). "Early cereals, referred to as “ancient wheat” (prevalent in the ancient Greek diet and endorsed by Galen of Pergamon as a fundamental food source), exert positive effects on insulin resistance, which underlies the pathophysiological mechanisms of liver steatosis and fibrosis." (PMID 39857800, 2025). "Pharmacological agents that mimic incretin activity or combine actions of multiple incretins have demonstrated significant metabolic benefits, including improved glycemic control, enhanced insulin sensitivity, reduction in hepatic steatosis, and meaningful weight loss." (PMID 41302136, 2025). "The present study found that T2DM patients with MASLD and metabolic hyperferritinemia had higher markers of liver steatosis and fibrosis (with an almost four-fold higher risk of advanced fibrosis), worse long-term glycemic control, and higher insulin resistance." (PMID 41010909, 2025).
Hepatic steatosis (continued). "As PTP1b activity rises, it may hinder the liver's ability to respond to insulin, which is closely linked to the development of hepatic steatosis and other metabolic disorders." (PMID 40007873, 2025). "Our findings provide novel evidence that higher adherence to the MIND score is significantly associated with reduced severity of MASLD, including lower hepatic steatosis and fibrosis scores, improved insulin sensitivity, reduced systemic inflammation, and favorable gut microbial profiles." (PMID 40927568, 2025). "In MASLD, higher HDL levels are also linked to improved insulin sensitivity and reduced hepatic steatosis, implying that this moderate elevation could have both metabolic and hepatic clinical relevance, even if the causal role of HDL per se remains debated." (PMID 41404533, 2025). "Hepatic steatosis, or fatty liver disease, is the abnormal accumulation of triglycerides (TGs) in liver cells, which occurs because insulin resistance causes the liver to increase both the production and uptake of fatty acids, resulting in the excessive storage of TGs as lipid droplets." (PMID 41356921, 2025). "Improvement of liver enzymes was explained by the direct action of GLP-1RAs on GLP-1 receptors located on the hepatocyte that enhances weight loss, insulin sensitivity, hepatic fat oxidation, reduces denovo lipogenesis, hepatic steatosis, and alleviates oxidative stress." (PMID 39633496, 2024). "Targeting the reduction of ferritin may mitigate the risk of liver steatosis arising from elevated insulin." (PMID 38926684, 2024). "Whilst weight loss was not imperative for clinically meaningful outcomes in MAFLD, the low-fat diet arm achieved ~ 4% weight loss and greater improvement in hepatic steatosis, visceral fat and insulin resistance (average of − 17%, − 76% and − 1.0 unit), respectively." (PMID 38717691, 2024). "The “first hit” consists of acquired insulin resistance to fat deposition and hepatic steatosis caused by excess fatty acids, and the “second hit” is the result of cellular and molecular changes involving oxidative stress, lipid peroxidation, inflammation, and fibrosis." (PMID 39064282, 2024). "Once activated, PAR2 also determines JNK 1/2 phosphorylation which inhibits insulin signaling, resulting in insulin resistance and subsequent liver steatosis associated with increased gluconeogenesis, through the activation of the lipogenic-regulatory transcription factor SREBP-1c." (PMID 39464875, 2024). "Our findings, which revealed a reduction in total TGs, DGs, and the TG/DG ratio following the LFSD intervention, coupled with a decrease in hepatic steatosis, suggests a potential association between these changes with improved lipid metabolism and insulin resistance." (PMID 38668319, 2024). "Our study provides credible evidence on the causal role of T2D and elevated insulin in liver steatosis and cirrhosis risk and indicates ferritin may play a mediating role in this association." (PMID 38926684, 2024). "Impaired insulin sensitivity disrupts the balance of glucose and lipid metabolism, increasing the risk of hepatic steatosis, and trivalent Cr, as a co-factor to activate the insulin receptor, improves insulin action in insulin-sensitive tissues, such as adipose, skeletal muscle, liver tissue, etc.." (PMID 38721033, 2024). "Importantly in the context of systemic glucose homoeostasis, Nogo-B interacts with the Nogo-B receptor (NgBR, encoded by NUS1) and knockout of Nus1 in mice causes hepatic steatosis, possibly be interfering with insulin signalling." (PMID 37137910, 2023). "In the case of hepatic steatosis, insulin signaling pathways are largely deficient." (PMID 36675217, 2023). "Further mechanistic studies revealed that Dyrk1b spontaneously causes fatty liver in rodents by increasing de novo lipogenesis and hepatic fatty acid uptake, despite suppressing the canonical insulin signaling by PKC epsilon-mediated insulin receptor inactivation." (PMID 37242206, 2023).
Hepatic steatosis (continued). "We observed that the increase in ASM/W and decrease in total fat mass were independently associated with the remission of hepatic steatosis, accompanied by significant improvements in insulin sensitivity and liver function in the group with an increase in ASM/W." (PMID 38115119, 2023). "GL is a heterogeneous congenital disease (CGL) or acquired disease (AGL) characterized by loss of adipose tissue and increased insulin resistance, and an increased predisposition to metabolic complications, such as DM, hypertriglyceridemia, and hepatic steatosis." (PMID 38169604, 2023). "The inhibition of hepatic steatosis is associated with many mechanisms, including reduced fat production, increased fatty acid β-oxidation, increased insulin sensitivity, the inhibition of oxidative stress, and the inhibition of activation of the inflammatory pathway." (PMID 36742427, 2023). "Hepatic steatosis and the associated lipotoxicity are associated with impaired insulin sensitivity." (PMID 37432201, 2023). "PTP1B inhibition may represent a promising drug target for NAFLD since its deficiency in mice enhanced insulin sensitivity and conferred resistance to diet-induced hepatic steatosis." (PMID 36678603, 2023). "Hepatic steatosis, in turn, may cause the liver to generate proatherogenic and proinflammatory mediators, aggravating hepatic and systemic insulin resistance." (PMID 36045348, 2022). "The inflammation of adipose tissue and the insulin resistance drive to an overload of fatty acids and glucose in the liver that causes hepatic steatosis, ER stress and activation of the unfolded protein response, generating the activation of the inflammasome and the cell death." (PMID 35185578, 2022). "Herein, we took advantage of the hepatocyte-specific PTEN knockout mice (LPTENKO), a model of hepatic steatosis associated with increased muscle insulin sensitivity and decreased adiposity, to identify potential secreted hepatic factors improving metabolic homeostasis." (PMID 35409319, 2022). "A recent interventional study in humans pointed in the same direction, showing that a short-term HFD, already known to induce liver steatosis and hepatic IR, also induced a low but significant increase in plasma fetuin-A level and is associated with reduced whole body insulin sensitivity." (PMID 36355106, 2022). "Consequently, the in vivo beneficial effects of SPE presented especially significant on ameliorating BW, eWAT, sWAT, insulin sensitivity, and NF-κB associated fatty liver." (PMID 36505243, 2022). "Moreover, osteopontin deficiency improved hepatic steatosis, insulin sensitivity and glucose homeostasis." (PMID 36145151, 2022). "Insulin‐sensitive hepatic Fasn expression is closely associated with the development of lipidosis leading to steatosis; the reduction in hepatic Fasn expression by all three treatments paralleled the reduction in circulating insulin and hepatic lipidosis." (PMID 35986566, 2022). "We identified the ten genera as a core set from the human gut microbiome, which could be a diagnostic biomarker of fatty liver diseases for insulin resistant individuals." (PMID 36528695, 2022). "We further examined whether the potent effect of krill oil supplementation on hepatic steatosis is associated with changes in gluconeogenesis and/or improved insulin sensitivity." (PMID 33572810, 2021). "It has been also shown that HFD may cause hepatic steatosis and changes in the balance of β-oxidation and oxidants, which in turn affects body weight, insulin signaling and other metabolic parameters." (PMID 33808007, 2021). "Apart from its effects on weight loss, GLP-1RA might play a direct role in improving hepatic steatosis through upregulations of insulin signaling pathways and fatty acid metabolism." (PMID 33897616, 2021).
Hepatic steatosis (continued). "Since hypothalamic melanocortin regulation is disrupted in Ay mice, sex differences in the severity of hepatic steatosis and insulin resistance may be associated mainly with the peripheral action of these hormones." (PMID 34943946, 2021). "We found that miR-21a-5p expression was decreased in PFD group, as well as, Srebf1 and Tgfb1. miR-21a-5p hepatic diminution has been associated with improved glucose tolerance and insulin sensitivity, in addition to prevent hepatic steatosis and fatty acid absorption." (PMID 34083664, 2021). "Fetuin-B, also a secreted hepatocyte factor, was upregulated in humans with liver steatosis and patients with type 2 diabetes, and it impairs insulin action in myotubes and hepatocytes and causes glucose intolerance in mice, while silencing of fetuin-B in obese mice improves glucose tolerance." (PMID 33777158, 2021). "Given our hypothesis that hepatic steatosis causes muscle insulin resistance and muscle protein loss, and to investigate a possible link between insulin resistance and muscle protein synthesis and breakdown rates, correlative analysis was performed." (PMID 34707570, 2021). "Women who are overweight or obese before menopause have a lower risk of hepatic steatosis and have a higher hepatic insulin sensitivity than men, which might contribute to a more beneficial cardiometabolic effect in women." (PMID 34680518, 2021). "Impaired hepatic FAO (most likely due to mitochondrial dysfunction in hepatocytes), increased circulating FFAs in the setting of basal VAT lipolysis (secondary to full-blown insulin resistance), and exaggerated lipogenesis, are considered pathogenic hallmarks of hepatic steatosis." (PMID 32604889, 2020). "Therefore, regardless of the type of alcoholic beverage, it was suggested that chronic consumption of alcohol was inversely associated with resistance to insulin and fatty liver." (PMID 32283773, 2020). "Abnormal hepatic insulin signaling is a cause or consequence of hepatic steatosis." (PMID 33105604, 2020). "A variety of mechanisms have been demonstrated to be implicated in preventing hepatic steatosis, including reducing lipogenesis, enhancing β-oxidation, increasing insulin sensitivity, suppressing oxidative stress, and inhibiting activation of inflammatory pathways." (PMID 32265720, 2020). "In the ‘two-hit hypothesis’, the first hit originates from the accumulation of more than 5% hepatic steatosis, during which insulin resistance emerges as a pathogenic contributor." (PMID 32660130, 2020). "In addition, AN1284 improved the metabolic profile of the mice, resulting in weight loss via increased fat oxidation, decreased hepatic steatosis, and enhanced insulin sensitivity." (PMID 32218769, 2020). "Furthermore, the IL-1β deficiency mice exhibited less hepatic steatosis and intact insulin sensitivity." (PMID 31736870, 2019). "It reduces insulin sensitivity at the levels of adipose tissue and liver, causing an accelerated hepatic fatty acid synthesis and an increased intrahepatic fat accumulation, which consequently results in hepatic steatosis, inflammation, and fibrosis." (PMID 31856189, 2019). "These include: augmented oxidative stress, modified iron homeostasis, activation of immunological and/or inflammatory processes leading to a disrupted cytokine imbalance and induction of hepatic steatosis, a risk factor in insulin sensitivity and related metabolic abnormalities." (PMID 30540839, 2018). "Hence, in the long-term, lower SREBP target gene expression upon imatinib was associated with reduced hepatic steatosis, systemic and adipose tissue inflammation and increased insulin sensitivity." (PMID 30333571, 2018). "The components of the healthy dietary pattern such as dietary fiber, vitamins, minerals, mono-, and poly-unsaturated fat may improve insulin sensitivity, increase antioxidative defense, reduce the risk of metabolic disorder, and decrease fatty liver disease." (PMID 29382113, 2018).